MIF (macrophage migration inhibitory factor)
Diseases named in the same sentence as MIF in open-access papers (continued):
Sharing a sentence is not in itself a finding about the gene and the disease.
infection (continued). "A study conducted on human patients suffering from visceral leishmaniasis due to infection with Leishmania donovani (L. donovani) showed that these patients had CD4+ T cells failing to express significant amounts of IFNγ and MIF, thereby failing to control infection." (PMID 35464430, 2022). "Bronchoalveolar lavage (BAL) at 72 h post-infection revealed an inflammatory expansion only in the MIF-sufficient animals, with an absence of eosinophils from Mif−/− airways and fewer macrophages with expression of RELMα only in wild-type mice." (PMID 35288645, 2022). "Blood MIF levels on admission were not different than those among survivors 3 months after infection, although we did not test MIF levels in control subjects." (PMID 33407905, 2021). "It has been shown that productive DENV2 and DENV3 infection can stimulate MIF release from human macrophages and Hep G2 cells without the requirement of MIF RNA transcription at 14 h post-infection." (PMID 32545679, 2020). "In addition, extracellular vesicles (EVs) have been identified as functional conveyors of MIF in obesity, as well as crucial mediators in platelet–leukocyte interactions upon DENV2 infection." (PMID 32545679, 2020). "Hepatic leukocytes from TgAlbCre-IL10-/- mice produced the highest levels of NO and IFN-γ, while the levels of IL-6, TNF and MIF were increased upon infection but not different between the groups." (PMID 32012211, 2020). "Macrophage migration inhibitory factor (MIF) plays a protective role in infection control in TB; however, to date, no studies on antibody responses to MIF have been reported." (PMID 33238656, 2020). "Another possibility is that in response to infection, red blood cells are stimulated to continuously release MIF independent of microvesicles." (PMID 32797076, 2020). "It was observed that in a cohort of children in an area endemic for amebiasis, those who lacked adequate amounts of antibodies against E. histolytica MIF were not protected from future infection." (PMID 31497025, 2019). "Many studies demonstrated the important protective role of IFN-γ, nitrite, IL-17A, MIF, TNF and IL-6 during infection by T. gondii." (PMID 30809216, 2019). "Our results demonstrated that CD74 (full-length isoforms) expression was higher in pregnant MIF-/- females than in their WT counterparts, regardless of infection." (PMID 29867817, 2018). "A slight increase in MIF levels due to infection was seen in both pregnant and non-pregnant females." (PMID 29867817, 2018). "In infected MIF-/- females, infection induced IL-6 upregulation only in non-pregnant females (P < 0.05)." (PMID 29867817, 2018). "Our results revealed that pregnant MIF-/- females presented higher amount of MC compared with pregnant WT ones, regardless of infection (P < 0.05)." (PMID 29867817, 2018). "In the MIF-/- group, the increase in IL-6 secretion, due to infection, was detected only in the non-pregnant mice (P < 0.01)." (PMID 29867817, 2018). "Our results demonstrated that MIF was slightly upregulated by infection in both pregnant and non-pregnant females, although statistical significance was not reached." (PMID 29867817, 2018). "Our results clearly demonstrated that pregnant MIF-/- females, regardless of infection, expressed more IDO at the maternal–fetal interface than its WT counterparts (P < 0.001)." (PMID 29867817, 2018). "The expression of TNF was increased due to infection in the WT group, only in pregnant females (P < 0.01), whereas in the MIF-/- group, infection induced increased TNF expression in both pregnant and non-pregnant females (P < 0.05)." (PMID 29867817, 2018). "Our data revealed MIF to be an important contributor to meningitic E. coli-induced cytokine production and tight junction disruption, while also showing that the NF-κB and MAPK signaling pathways are involved in the infection process." (PMID 30340642, 2018).
infection (continued). "Regarding the Th2 cytokine profile, IL-4 expression was apparently increased because of infection in both groups, but this upregulation was statistically significant only in infected/non-pregnant MIF-/- females (P < 0.05)." (PMID 29867817, 2018). "Pyrimethamine did not significantly alter the MIF levels when compared to untreated cells, regardless of the infection." (PMID 28798905, 2017). "We demonstrate that serum MIF increased rapidly during the acute infection with T. gondii and promoted maturation of CD11b+ but not CD8α+ DCs." (PMID 27057101, 2016). "The results of the present study suggested that MIF is not expressed under simple trauma conditions but is expressed in conjunction with infection." (PMID 23251299, 2013). "In untreated rabbits, most of these genes were progressively induced by Mtb infection from 4 to 8 weeks, and many had reached a plateau (IFN-γ, IL13, IL6, MIF, CCL4, NFκB, APRIL, TLR2, RAB7 and LAMP2) or were even reduced (IL10, CXCR3, GMCSF and PI3K3) by 12 weeks post-infection." (PMID 21949656, 2011). "In contrast, in the MIF KO mice, there were less infiltrating PMNs, less edema, and no destruction of the epithelial layer when either strain 6294 or PAO1 were used to induce infections." (PMID 20361053, 2010). "RANTES, MIF, MCP3 and CXCL5, showed increased transcription during the infection." (PMID 22331987, 2010). "MIF is expressed in multiple immune and nonimmune cell types and is released in response to infection and other stresses." (PMID 19413900, 2009). "The data indicated that the protein expression levels of MIF and CD74 in the spleen were downregulated in the infection group (p < 0.001), while levamisole and 25–100 mg/kg baicalin could increase CD74 protein level in the spleen compared to the infection group (p < 0.05)." (PMID 40427533, 2025). "Our transcriptome data in TS cells do not show an increase in MIF gene expression after infection." (PMID 38771057, 2024). "Moreover, several additional immune proteins, including insect resistance 3 protein IR3, mildew resistant locus O-like protein MLO, wheatwin-2, patatin and macrophage migration inhibitory factor MIF, were also differentially regulated by Kac following PP.CN1.0 infection." (PMID 36564751, 2022). "The infection of both EBV and HPV may have some influence on MIF and macrophage polarization." (PMID 34407796, 2021). "MIF protein increased significantly by BAFF-var in the absence of infection, in agreement with a protective role during Plasmodium infection, as elevated MIF levels correlated with the severity of cerebral and placental malaria and with protection from severe childhood malaria." (PMID 33123155, 2020). "MIF is constitutively produced by untreated human IECs in vitro and in vivo, biologically active, and inhibits the migration of macrophages when there is no infection." (PMID 33194815, 2020). "Moreover, MIF has been shown to induce MAPK activation within Type II alveolar epithelial cells, leading to enhanced cellular proliferation, potentially contributing to repair of damaged alveolus in response to infection." (PMID 32707845, 2020). "However, infection of macrophages with Sindbis virus resulted in MIF release from intracellular pools without a significant increase in MIF transcription or cell death." (PMID 32545679, 2020). "One obstacle to such an experiment is that appropriate migration of the adoptively transferred population to the site of infection may not occur, particularly given that MIF is thought to arrest macrophage migration in situ." (PMID 31708913, 2019). "High-throughput proteomic sequencing based on isobaric tags for relative and absolute quantitation showed that chicken macrophage migration inhibitory factor (chMIF) was upregulated uniquely in primary bursal cells infected with vvIBDV compared with infection by nonpathogenic attenuated IBDV." (PMID 31632367, 2019).
infection (continued). "Overall, results indicate that, at 7 days post-infection, viral production from initially unactivated CD4+ T-cells is significantly higher upon exposure to supernatants derived from infected MDMs treated with 1 ng/ml MIF, compared to exposure to supernatants derived from uninfected MDMs." (PMID 29997630, 2018). "Thus, the aim of this work was to study the effect of MIF/CD74 interaction on the phenotype and the function of primary HIV-infected MDMs, and how this axis determines the environment to modulate CD4+ T-cell permissiveness to infection." (PMID 29997630, 2018). "Also, IDO expression was upregulated in pregnant relative to non-pregnant MIF-/- females, regardless of infection (P < 0.05)." (PMID 29867817, 2018). "We therefore raised the question of whether MIF-treated MDM-derived supernatants could promote the infection of unactivated primary CD4+ T-cells in the absence of other stimuli." (PMID 29997630, 2018). "We also examined whether the absence of p47phox influenced the activation of MIF by infection with T. gondii in macrophages." (PMID 28743960, 2017). "Data obtained from ELISA demonstrated that enrofloxacin and toltrazuril increased IL-6 and MIF production in BeWo cells infected by T. gondii, regardless of strain, while in the absence of infection, enrofloxacin induced only high IL-6 levels and toltrazuril triggered high IL-6 and MIF levels." (PMID 28798905, 2017). "In contrast, Mif−/− mice lacked serum MIF throughout the acute infection." (PMID 27057101, 2016). "The predication that IL-16C and MIF are released by secondary necrotic neutrophils is strengthened by our results that after UV light irradiation and infection with A. phagocytophilum, IL-16 and MIF release is in line with enhanced secondary necrosis, but not with apoptosis." (PMID 27551482, 2015). "MIF gene expression level in liver, spleen and bone marrow was characterized by two distinct phases, i.e. an initial increase during the acute phase of infection that returns back to the level of non-infected mice, followed by a second more progressive increase during the chronic phase of infection." (PMID 25255103, 2014). "If the differences in the results reflect the differences between infection, represented by macrophages and LPS, and trauma, represented by PMNs and fMLP, no MIF expression is expected in cases of trauma and only MIF would be expressed in cases where trauma is combined with infection." (PMID 23251299, 2013). "In first-trimester villous explants, MIF is upregulated, and it can control T. gondii infection, whereas a lack of MIF upregulation, after infection, in third-trimester placental explants may be related to a higher susceptibility to infect at this gestational stage." (PMID 31068920, 2019). "In sum, the improved viral production observed in CD4+ T-cells after treatment with supernatants derived from 25 ng/ml MIF-treated infected MDMs could not to be explained by differential cell viability, infection percentage, or cell activation (measured by surface markers)." (PMID 29997630, 2018). "In the absence of infection, the treatment with all four oleoresins and SDZ + PYR did not alter IL-6 and MIF production in comparison to uninfected and untreated villous explants (control group)." (PMID 32938966, 2020). "Again, our results demonstrated an upregulation of Th1 (IFN-γ, TNF, and IL-6) cytokines due to infection, significantly for IFN-γ in both MIF-/- and WT groups, regardless of pregnancy (P < 0.05)." (PMID 29867817, 2018). "After infection of CMH5 with PRU, at 8 h post infection, we observed a non-significant synthesis for interleukins (IL-6 and IL-8), chemokines (MCP-1, MIF and GROα), growth factors (G-CSF and GM-CSF) and SERPIN E1." (PMID 24886982, 2014). "Yet, absence of MIF slightly increased survival time and reduced serum IFN-γ, TNF, and IL-6 concentrations while inducing IL-10 production in the chronic stage of infection." (PMID 25255103, 2014).
infection (continued). "Although MIF can induce CCL2 and trigger monocyte recruitment and subsequent arrest in tissue, the bone marrow emigration and recruitment of inflammatory monocytes in tissues during the acute stage of infection was found independent of MIF." (PMID 25255103, 2014).
cardiovascular disease (32 papers, 2010 to 2025). "Based on up-to-date information, there are no current clinical research programs aimed at identifying the MIF or testing MIF-associated agonism/antagonism in the context of cardiovascular disease." (PMID 39202723, 2024). "Since patients with ESRD are characterized by the highest cardiovascular disease risk, we assessed MIF plasma levels in patients with ESRD undergoing maintenance HD before, during and after a HD session." (PMID 26485680, 2015). "In addition, MIF is implicated in cardiovascular diseases (CVD), acting as a reliable biomarker of disease severity and being readily detectable in the blood and at sites of inflammation." (PMID 38476376, 2024). "Hence, MIF might be a potential biomarker to predict the severity and the risk of ACS and to suggest therapies that target MIF pathways as attractive treatment options for cardiovascular diseases." (PMID 22693633, 2012). "This approach would address current gaps in tailored chemokine-selective targeting strategies and receptor-specific MIF therapeutics in inflammatory and cardiovascular diseases." (PMID 33239628, 2020). "The soluble CD74 ECD has already been connected to signaling functions in context of the macrophage migration inhibitory factor (MIF) related to cardiovascular diseases." (PMID 33381526, 2020). "MIF is a chemokine-like cytokine that plays a role in the pathogenesis of inflammatory and cardiovascular disorders." (PMID 29581527, 2018). "MIF’s role in cardiovascular disease is dual, as it also has a clear-cut cardioprotective role in the setting of myocardial ischemia and reperfusion (I/R) injury, contrasting the bonafide negative function in the promotion of arteriosclerosis development." (PMID 29728137, 2018). "There are also studies that have investigated the relationship between MIF and cardiovascular disease." (PMID 30483634, 2017). "With regard to increasing amounts of literature on the role of MIF in cardiovascular diseases and the increased cardiovascular risk in ESRD, we here aimed to investigate the impact of HD on MIF plasma levels in ESRD patients." (PMID 26485680, 2015). "MIF is an upstream regulator of the host innate and adaptive immune response, and, if dysregulated, is a key driver of acute and chronic inflammation, and cardiovascular diseases including atherosclerosis." (PMID 33239628, 2020). "With regard to diagnostic markers that might reflect changes in metabolic, inflammatory, and cardiovascular diseases, the cytokine macrophage migration inhibitory factor (MIF) plays an emerging role." (PMID 29728137, 2018). "Because of the tissue-specific expression of MIF, a MIF agonist such as MIF20 may provide a unique way to up-regulate AMPK in the treatment of cardiovascular disease." (PMID 27478687, 2014). "In particular, the up-regulation of MIF, CLP36 and GLO1, which are associated with anti-apoptotic, cytoskeleton binding, and detoxifying activities, gives new insights into the understanding of SF pleiotropic behavior in counteracting cardiovascular diseases." (PMID 24349480, 2013). "Recent studies also suggested a direct link between MIF and cardiovascular disease." (PMID 21283592, 2011). "Macrophage migration inhibitory factor (MIF), a widely expressed pleiotropic cytokine, is reportedly involved in several cardiovascular diseases, in addition to inflammatory diseases." (PMID 30983881, 2019). "Thus, MIF rejuvenated aged MSCs by activating autophagy and enhanced their therapeutic efficacy in MI, suggesting a novel MSC-based therapeutic strategy for cardiovascular diseases in the aged population." (PMID 31881006, 2019).
kidney disease (24 papers, 2010 to 2026). "Direct evidence for a role of MIF in the DTH response associated with kidney disease comes from the findings that treatment with a neutralizing anti-MIF antibody inhibits skin DTH reaction in the primed mouse model of anti-GBM crescentic GN." (PMID 35563296, 2022). "We have here described the current evidence of MIF being a mediator in a number of diseases and conditions associated with kidney disease." (PMID 26858715, 2016). "It has been shown that MIF -173 G > C gene polymorphism may be associated with renal disease susceptibility, particularly in children." (PMID 28507475, 2017). "Furthermore, urinary MIF has been proposed as a diagnostic tool in kidney disease." (PMID 28813470, 2017). "Renal MIF was shown to possess a renoprotective function in different kidney diseases, also including acute kidney injury." (PMID 36631486, 2023). "The development of the neutralizing MIF antibody provided the first evidence of anti-MIF treatment in kidney diseases." (PMID 35563296, 2022). "There are two potential therapeutic options for kidney diseases in terms of targeting MIF: the antibody-based and small molecule inhibitors or antagonists." (PMID 35563296, 2022). "Given the critical position of MIF in the upstream inflammatory cascade, this review focuses on the regulatory role and molecular mechanisms of MIF in kidney diseases." (PMID 35563296, 2022). "CCL2 blockade attenuates glomerular and interstitial infiltration of pro-inflammatory macrophages, but other chemokines such as CX3CL1, CXCL16, and macrophage migration inhibitory factor (MIF), also contribute to macrophage recruitment in kidney disease." (PMID 36232403, 2022). "We find that proinflammatory macrophages produce abundant MIF in both experimental and human kidney disease, including renal allograft rejection." (PMID 35563296, 2022). "Studies in mice and in humans demonstrate the therapeutic potential of MIF inhibition for kidney diseases." (PMID 35563296, 2022). "Interstitial macrophage accumulation in this model was associated with up-regulation of tubular expression of the chemotactic molecules, MCP-1 and MIF, which have been shown to promote monocyte recruitment in a several models of kidney disease." (PMID 26909597, 2016). "Future interventional studies are needed to delineate the role of MIF as a treatment target in clinical kidney disease." (PMID 26858715, 2016). "Moreover, the expression of certain CD74 ligands such as MIF, is also upregulated in kidney disease, which stimulates the expression of inflammatory mediators in TECs and podocytes and promotes inflammatory cells infiltration by interacting with CD7442-45." (PMID 38904010, 2024). "ISO-1 is the first MIF inhibitor and has been well studied in several experimental kidney diseases." (PMID 35563296, 2022). "The therapeutic potential of targeting MIF signaling to treat kidney diseases is also discussed." (PMID 35563296, 2022). "In this review, we will focus on the immunological functions of MIF in kidney diseases." (PMID 35563296, 2022). "Moreover, in kidney diseases, MIF contributes significantly to macrophage and T lymphocyte accumulation contributing to progressive renal injury." (PMID 31514750, 2019). "While MIF has been implicated in glomerular and tubulointerstitial injury, very little is known about D-dopachrome tautomerase (DDT), a second ligand for CD74, in kidney disease." (PMID 29924850, 2018). "In humans, the role of MIF in kidney disease is less well described." (PMID 28813470, 2017). "MIF as a specific inhibitor may have therapeutic potential for patients with inflammatory and fibrotic kidney diseases." (PMID 27313397, 2016). "MIF expression is upregulated in acute and chronic, human, and experimental kidney diseases." (PMID 26441987, 2015). "Therefore, patients who are impacted by steroid-resistant kidney disease may have favorable outcomes if a blocking agent targeting MIF is used instead of glucocorticoids." (PMID 40968277, 2026).